EIF3G (eukaryotic translation initiation factor 3 subunit G)
Description:
RNA-binding component of the eukaryotic translation initiation factor 3 (eIF-3) complex, which is required for several steps in the initiation of protein synthesis. The eIF-3 complex associates with the 40S ribosome and facilitates the recruitment of eIF-1, eIF-1A, eIF-2:GTP:methionyl-tRNAi and eIF-5 to form the 43S pre-initiation complex (43S PIC). The eIF-3 complex stimulates mRNA recruitment to the 43S PIC and scanning of the mRNA for AUG recognition. The eIF-3 complex is also required for disassembly and recycling of post-termination ribosomal complexes and subsequently prevents premature joining of the 40S and 60S ribosomal subunits prior to initiation. The eIF-3 complex specifically targets and initiates translation of a subset of mRNAs involved in cell proliferation, including cell cycling, differentiation and apoptosis, and uses different modes of RNA stem-loop binding to exert either translational activation or repression. This subunit can bind 18S rRNA. (Microbial infection) In case of FCV infection, plays a role in the ribosomal termination-reinitiation event leading to the translation of VP2.
Synonyms: EIF3S4; eIF3-delta; eIF3-p44; EIF3-P42
Tractability: Small molecule: a structure with a bound ligand is known. PROTAC: ubiquitination databases record sites on it; its protein half-life has been measured.
Gene: Protein-coding gene on chromosome 19 (10,115,010 to 10,119,951, reverse strand). Ensembl gene ENSG00000130811.
Subcellular location: Cytoplasm; Nucleus; Cytoplasm, perinuclear region
Subcellular location (Human Protein Atlas): Cytosol
Pathways (Reactome):
Metabolism of proteins: Formation of a pool of free 40S subunits; Formation of the ternary complex, and subsequently, the 43S complex; GTP hydrolysis and joining of the 60S ribosomal subunit; L13a-mediated translational silencing of Ceruloplasmin expression; Ribosomal scanning and start codon recognition; Translation initiation complex formation
Gene Ontology:
Molecular function: protein binding; RNA binding; translation initiation factor activity; nucleic acid binding
Biological process: translational initiation; viral translational termination-reinitiation; formation of cytoplasmic translation initiation complex; cytoplasmic translational initiation
Cellular component: cytoplasm; cytosol; eukaryotic translation initiation factor 3 complex; nucleus; eukaryotic 43S preinitiation complex; eukaryotic 48S preinitiation complex; perinuclear region of cytoplasm
Genetic constraint (gnomAD): Loss-of-function variants: 10 observed, 41.54 expected, observed/expected ratio (o/e) 0.24, 90% interval 0.15 to 0.41. The upper end of that interval is the gene's LOEUF score, 0.41, which puts it in group 1 of 6, group 1 being the genes least tolerant of losing a copy. Missense variants: 297 observed, 452.98 expected, observed/expected ratio (o/e) 0.66, 90% interval 0.6 to 0.72. Synonymous variants: 204 observed, 177.9 expected, observed/expected ratio (o/e) 1.15, 90% interval 1.02 to 1.29.
Homologues: Orthologues: macaque EIF3G (100% identical), dog EIF3G (99% identical), guinea pig EIF3G (99% identical), chimpanzee EIF3G (98% identical), mouse Eif3g (98% identical), pig EIF3G (98% identical), rat Eif3g (97% identical), tropical clawed frog eif3g (82% identical), zebrafish eif3g (81% identical), Drosophila melanogaster eIF3g1 (40% identical), Drosophila melanogaster eIF3g2 (40% identical), Caenorhabditis elegans eif-3.G (31% identical).
Diseases named in the same sentence as EIF3G in open-access papers:
EIF3G is named in the same sentence as 21 diseases in open-access papers, as found by Europe PMC text mining. Sharing a sentence is not in itself a finding about the gene and the disease. The quoted sentences say what the papers report.
bladder cancer (4 papers, 2021 to 2025). "For instance, EIF3G modulates the mTOR signaling pathway, inhibiting the proliferation and metastasis of bladder cancer cells." (PMID 41277807, 2025). "The molecular mechanisms involved in bladder cancer mainly involve EIF3G-related translational activation as well as mTOR signaling pathway activation." (PMID 36755568, 2023). "It is consistent with observations in colorectal cancer and bladder cancer, where depletion of EIF3G alone inhibits cell growth." (PMID 35409343, 2022). "In addition, via inhibiting the mTOR signaling pathway by directly binding to the EIF3G protein, exogenous overexpression of LINC02446 could inhibit cellular proliferation, migration and invasion in bladder cancer." (PMID 34631703, 2021).
colon cancer (2 papers, 2023 to 2024). "As subunits in the eIF3(a:b:i:g) subcomplex, only eIF3a and eIF3i, but not eIF3b and eIF3g, are overexpressed in human colon cancers compared with their matching normal tissues." (PMID 39413959, 2024).
colorectal cancer (2 papers, 2022 to 2023). A primary or metastatic malignant neoplasm that affects the colon or rectum. "Specifically, the eukaryotic translation initiation factor 3 subunit G (EIF3G) is implicated in the progression of human colorectal cancer." (PMID 38148841, 2023).
narcolepsy (2 papers, 2021 to 2024). A sleep disorder characterized by a tendency for excessive sleepiness during the day which occurs even after adequate sleep in the nighttime. "For example, the altered expression of eIF3g is associated with narcolepsy and also observed in an animal model for autism." (PMID 38886018, 2024). "The eIF3 complex is widely implicated in brain disorders, and deregulated eIF3g is specifically linked to narcolepsy." (PMID 34323215, 2021). "The altered expression of eIF3g is linked to narcolepsy and autism." (PMID 38886018, 2024). "Furthermore, a single-nucleotide polymorphism located in the intron of human eIF3g elevates its mRNA levels and is associated with narcolepsy." (PMID 34323215, 2021).
atherosclerosis (1 paper, 2024). A disease characterized by the build-up of fatty material and calcium deposition in the arterial wall resulting in partial or complete occlusion of the arterial lumen. "Mitochondrial and metabolism-related genes such as NDUFS7, TMEM126B, and EIF3G were clustered together, indicating a metabolic impairment in atherosclerosis." (PMID 39120300, 2024).
benign adenoma (1 paper, 2024). "Additionally, the expression of both eIF3a and eIF3i but not eIF3b and eIF3g is also increased in benign adenoma polyps." (PMID 39413959, 2024).
breast carcinoma (1 paper, 2022). "In our report, EIF3G/ K/ L was down-regulated in breast cancer tissues compared with normal tissues, while EIF3J presented the opposite trend." (PMID 35040374, 2022).
ductal breast carcinoma (1 paper, 2022). "A low expression level of EIF3G was found in ductal breast carcinoma in the Richardson dataset." (PMID 35040374, 2022).
cancer (5 papers, 2014 to 2024). A tumor composed of atypical neoplastic, often pleomorphic cells that invade other tissues. "Three subunits of the eukaryotic initiation factor 3 (eIF3) complex are correlated with cancer development—subunit eIF3d possesses cap-binding activity; eIF3G is associated with cancer progression; eIF3h interacts with METTL3." (PMID 33808751, 2021). "Western blotting showed that the expression of cyclin B1 and cyclin D1 was decreased by the downregulation of EIF3G, suggesting that the cell cycle and mitotic events are controlled by EIF3G in cancer cells." (PMID 34202873, 2021). "eIF3i expression is also significantly increased by ~5 fold in cancer compared with their matched normal tissues, consistent with the previous finding, Interestingly, the expression of both eIF3b and eIF3g did not change significantly between cancer and normal tissues." (PMID 39413959, 2024). "Here, our results further support the conclusion that eIF3G is a target for the anti-cancer properties of SAHA for the treatment of HCC and possibly other types of cancers and that its therapeutic benefit would be independent of a potential increased expression level of eIF3G." (PMID 25166596, 2014). "DHX8, EIF3G, RBM22, U2AF1 UPF1 and YBX-1 are also candidates therapeutic targets for cancer therapy because the tumor cell progression was strongly inhibited by the downregulation of these RBPs in cancer cells, including HCT116, SUIT2 and OE33 cells, but not in non-cancerous cells." (PMID 34202873, 2021).
tumor (5 papers, 2008 to 2023). "Functional assays revealed that EIF3G overexpression enhances HCT-116 cell proliferation, migration, and xenograft tumor growth, whereas xenograft tumors derived from EIF3G-silenced HCT116 cells exhibited reduced weights and volumes compared to those from control cells." (PMID 38148841, 2023). "The translation initiation factor eIF3G has never been demonstrated to play an important role in tumor development." (PMID 25166596, 2014).
EIF3G also shares sentences with these, for which no sentence is quoted: Acute hepatitis (1 paper); autism (1); brain disorder (1); ductal breast carcinoma in situ (1); epilepsy (1); esophageal cancer (1); hepatocellular carcinoma (1); liver diseases (1); lung carcinoma (1); mastitis (1); platelet disorders (1).